ENSG00000266718 (novel transcript, antisense MYO1D)
Gene: Long non-coding RNA gene on chromosome 17 (32,495,536 to 32,500,910, forward strand). Ensembl gene ENSG00000266718.
Gene Ontology:
Biological process: SRP-dependent cotranslational protein targeting to membrane, signal sequence recognition
Cellular component: signal recognition particle, endoplasmic reticulum targeting